PRAME (PRAME nuclear receptor transcriptional regulator)
Diseases named in the same sentence as PRAME in open-access papers (continued):
Sharing a sentence is not in itself a finding about the gene and the disease.
tumor (continued). "PRAME is a member of the retinoic acid receptor (RAR) signaling pathway that may act as an oncogene or as a tumor suppressor depending on the cellular context." (PMID 38067388, 2023). "Higher ICI-4W expression of extracellular matrix (ECM) genes, including trypsinogens (PRSS1 and PRSS2) and matrix metalloproteases, and genes encoding cancer antigens (CTAG2, SAGE1, MAGEA1/A4/A10, POTEE, and PRAME) was significantly associated with ICI resistance and tumor growth during ICI-4W." (PMID 37433281, 2023). "PRAME was found as a tumor-promoting gene in hematological system neoplasms." (PMID 36980687, 2023). "Nude mice were used to confirm the role of PRAME in tumor growth in vivo." (PMID 36980687, 2023). "In vivo also substantiated that PRAME promoted tumor growth." (PMID 36910848, 2023). "While there are many interactions to consider when looking at the role of PRAME in the tumor pathogenesis of UM, our group wanted to understand PRAME’s intrinsic disorder propensity and its potential to provide a framework for developing biologics or immunotherapies to target PRAME." (PMID 37626310, 2023). "According to the TCGA data, in particular PRAME is expressed in various other tumor types as well." (PMID 37026005, 2023). "Therefore, the effect of overexpressed PRAME on the growth of primary tumor xenografts was investigated in nude mice." (PMID 36910848, 2023). "These T-cell clones effectively recognized all PRAME or CTCFL positive OVCA/tumor cell lines." (PMID 37026005, 2023). "In addition, a similar expression pattern of PRAME in an expanded sample size with 519 tumor samples of HNSC and 44 normal tissue samples was revealed from the online database of GEPIA." (PMID 36910848, 2023). "This implies that PRAME expression may be involved in immune escape mechanisms during carcinogenesis and may potentially indicate an immune cold tumour environment." (PMID 36980267, 2023). "PRAME may promote tumor progression through the inhibition of differentiation, growth arrest, and apoptosis induced by retinoic acid." (PMID 37626310, 2023). "Thirty TCR sequences were cloned into a retroviral vector, transferred into recipient T-cells by retroviral transduction, and analyzed for expression of the TCRs on the cell surface, as well as for antigen-specific recognition of PRAME-positive, HLA-A2-positive tumor cell lines." (PMID 35454906, 2022). "PRAME expression was associated with the largest basal diameter (LBD) and tumor volume." (PMID 35328098, 2022). "PRAME has been extensively investigated as a target for immunotherapy, however, its role in modulating the anti‐tumour immune response remains largely unknown." (PMID 34612587, 2021). "In this study, we investigated whether PRAME tumour expression could be involved in modulating anti‐tumour immunity." (PMID 34612587, 2021). "PRAME was found to be highly expressed in human adult germ cells and various tumor types." (PMID 33503926, 2021). "This particular tumor displayed the second highest levels of PRAME expression, suggesting that it could have originated from such a class I tumor." (PMID 32313009, 2020). "PRAME expression was observed in 75–100% of the tumour cells of two mUM only." (PMID 33008022, 2020). "Interestingly, PRAME+ status was positively correlated with larger tumor diameter after analysis of the TCGA Research Network dataset." (PMID 32992823, 2020). "In recent years, however, it has become apparent that PRAME could promote tumor development and progression via different mechanisms." (PMID 31311081, 2019). "PRAME is a tumour antigen that induces a cytotoxic T-cell immune response." (PMID 31391080, 2019). "This raises the question of whether PRAME could be involved in regulating the adaptive anti-tumor immune response, corroborating its value as an immunotherapeutic target in comparison to other CTAs." (PMID 31311081, 2019).
tumor (continued). "As a first challenge, the heterogeneity of PRAME expression could likely present a bottleneck for the efficient targeting and complete eradication of tumor cells." (PMID 31311081, 2019). "Thus, we explored the expression of PRAME in both solid cancer types using the TCGA data repository and found a significant increase in PRAME expression in the tumor tissues compared to normal tissues." (PMID 30602372, 2019). "Secondly, tumor types that are defined as PRAME-positive might display significant intra-tumoral heterogeneity, leading to treatment resistance due to the low expressing cell clones." (PMID 31311081, 2019). "Amongst all tumor types with TCGA data, PRAME was most frequently amplified in HGSC." (PMID 27322684, 2016). "The PRAME tumour antigen is expressed in several tumour types but in few normal adult tissues." (PMID 27843625, 2016). "Since we found that PRAME+ correlates significantly with tumor size, this multi-center study will also evaluate whether there is a minimum threshold tumor size at which point PRAME becomes prognostic." (PMID 27486988, 2016). "The activation of similar cytokine signalling pathways in cancer cells might therefore account for the expression of PRAME in tumours, and its low levels in normal tissues." (PMID 23460923, 2013). "These insights will aid future efforts to establish whether PRAME expression in tumours has roles in the initiation or progression of haematological malignancies, and/or in immune responses to infection." (PMID 23460923, 2013). "The restricted expression pattern of PRAME in normal tissues and its overexpression in tumours renders it a useful marker of minimal residual disease after chemotherapy, and an attractive target for immunotherapy, particularly in acute myeloid leukaemia (AML) and chronic myeloid leukaemia (CML)." (PMID 23460923, 2013). "In normal tissues, PRAME is expressed in the testis, adrenal gland, ovary, and endometrium, and its expression levels are lower by more than 3 logarithmic series compared with that in tumor tissues." (PMID 23691459, 2012). "The physiological functions of PRAME in normal and tumour cells are unknown, although a role in the regulation of retinoic acid signalling has been proposed." (PMID 20799951, 2010). "This raises the possibility that PRAME may have different roles in oncogenesis or tumour suppression dependent on the tumour type." (PMID 20799951, 2010). "However, earlier studies have reported CLU as down-regulated and CAPG and PRAME as up-regulated in advanced carcinomas compared to early tumours or normal tissue." (PMID 19775429, 2009). "Analysis of a number of other genes that are strongly and specifically expressed in tumour over normal lung, including SERPINB5, TERT and PRAME, showed marked allelic expression imbalances in the tumour tissue in the context of balanced or only marginally imbalanced relative allelic copy numbers." (PMID 16222316, 2005). "Moreover, a low level of histidine phosphatase LHPP was correlated with high PRAME expression in PRAME-positive UM tumor cells, but opposite phenomenon as high level of histidine kinase (NME1 and NME2), which indicates that low LHPP expression forebodes a risk of easier metastasis." (PMID 40988976, 2025). "Small tumors were more likely than larger tumors to be Class 1 (p < 0.0001), PRAME(−) (p = 0.004), BAP1wt (p = 0.0006), and to lack any BSE mutation (p = 0.001), suggesting that most or all UM begin as small Class 1 tumors that later acquire a BSE mutation during tumor growth." (PMID 41387680, 2025). "In this context, the overexpression of PRAME may be a mechanism by which tumour cells can escape tumour suppressor RAR signalling, e.g., by interacting with RAR in a ligand-dependent manner and inhibiting RAR-dependent transactivation by interacting with PcG complexes." (PMID 38338862, 2024).
tumor (continued). "Furthermore, PRAME expression has been associated with tumor grade and negative estrogen receptor status, signifying its potential utility in delineating high-risk BC cases." (PMID 37958210, 2023). "In addition to using proliferation, apoptosis, and Wnt pathway regulation to explain the tumor-promoting effect of PRAME, the targets that directly connect between PRAME and the Wnt/β-catenin signaling pathway and the detailed mechanisms thereof need to be clarified." (PMID 36980687, 2023). "However, the molecular functions of PRAME in tumor cells remain largely unknown and may differ among different tissue types." (PMID 35076507, 2021). "Moreover, PRAME can act as an oncogene or a tumor-suppressor gene in different cancer types." (PMID 34178030, 2021). "Interestingly, in our study, NY-ESO-1 and PRAME were expressed more often in tumours with low TILs." (PMID 33287125, 2020). "Interestingly, antibody-based targeting of PRAME has emerged as a novel approach, which could offer a new avenue to induce potent anti-tumor responses." (PMID 31311081, 2019). "This phenomenon is not restricted to PRAME but has also been observed when targeting other tumor-associated, but not tumor-selective, antigens, and it might be related to the negative selection of high affinity T cell responses in the thymus." (PMID 31311081, 2019). "Therefore, PRAME is a feasible candidate targeting antigen for tumor immunotherapy or vaccines." (PMID 23691459, 2012). "Thus, while anti-PRAME vaccines are currently being evaluated in clinical trials for their efficacy against PRAME-positive tumours, combination with demethylating agents to maximise CTA expression may be required for complete elimination of the tumour cells." (PMID 20799951, 2010). "PRAME expression was associated with tumour grade and negative oestrogen receptor status." (PMID 18648365, 2008). "PRAME mRNA expression in BM or PB was compared before and after IMP infusion to assess the impact of MDG1011 on tumor burden." (PMID 41008812, 2025). "We found more than one TA was expressed per tumor, and seven TAs (GPC3, IGF2BP3, NOL4, NR6A1, PKB, PRAME, and SPAG17) were detected in multiple tumors." (PMID 40894019, 2025). "Treatment with HMA in MDS results in the upregulation of previously methylated and silenced tumor genes that express antigens such as NY-ESO-1, MAGE-A3, PRAME, and WT1." (PMID 39199554, 2024). "The CTAs PRAME, CT45A1, and MAGEC2 are known to induce epithelial-to-mesenchymal transitions (EMTs) in tumor cells." (PMID 39451258, 2024). "Further research must be carried out to better understand the role of PRAME in cancer through its involvement in RAS, EMT promotion, and establishment of a tumor-cold microenvironment." (PMID 39451258, 2024). "The tumour cells were diffusely and intensely positive for multiple melanocytic markers: MelanA, S100, SOX10, and PRAME." (PMID 39001214, 2024). "We have previously shown that exercise mobilized T-cells and γδ T-cells proliferate better ex vivo in response to tumor antigen (e.g. WT1, PRAME) peptide loaded dendritic cells and phosphate antigens, respectively." (PMID 37077913, 2023). "Recently, it has been reported that PRAME forms a complex with p14/alternate reading frame (ARF) (CDKN2A), a well-established tumor suppressor, as well as with Cullin 2 RING E3 ligases." (PMID 38132219, 2023). "The other five top-rated CTAs CT45, IMP3, KIF20A, PRAME, and SP17 were similarly promising, and reached 8.07 points, due to a lower tier in “Expression on tumor Stem Cells”." (PMID 36768616, 2023). "To elucidate the presence and prognostic role of these factors and TAAs in HL we conducted NanoString analysis on primary tumor biopsies and found high expression of CT45A1, PRAME, Survivin, and other TAAs." (PMID 34584203, 2022). "The TAA/ABL1 mRNA ratios in the tumor cell line-spiked samples were highly reproducible, with a CV of 0.05 and 0.11 for WT1/ABL1, 0.1 and 0.21 for PRAME/ABL1, and 0.12 and 0.21 for BIRC5/ABL1." (PMID 36248870, 2022).
tumor (continued). "A total of 10 of these tumour cohorts have MAGE group members in their top-25 upregulated genes; 3 (BRCA, HNSC, LUAD) have both MAGEs and PRAME in their top-25 upregulated genes." (PMID 36499258, 2022). "These CTLs recognized and had cytotoxic activity against PRAME-expressing tumor cell lines and primary CML cells, demonstrating the potential of PRAME in cancer vaccine development for CML treatment." (PMID 33503926, 2021). "PRAME and NY-ESO-1 expression levels are correlated to patient survival and tumour grade in opposing ways, while both CTAs are correlated with low TIL counts." (PMID 33287125, 2020). "PRAME and NY-ESO-1 expression levels are correlated to patient survival and tumour grading in opposing ways, while both CTAs are more frequent in tumours with low TIL counts." (PMID 33287125, 2020). "Starting from a healthy donor leukopak, CD8+ T cells were generated using an aAPC cocktail loaded with 5 HLA-A2 epitopes from AML tumor antigens WT1, PRAME and cyclin A1." (PMID 30400835, 2018). "However, since we show here that PRAME expression is strongly associated with larger tumor size, a study composed primarily of large tumors may not accurately reflect the true range of PRAME expression." (PMID 27486988, 2016). "Limitations of our study are that we were unable to test the patients' tumor expression for MAGE and PRAME, although HER2 expression was demonstrated by standard immunohistochemistry in the primary tumor of the patient who developed anti-HER2 T cell responses." (PMID 28837000, 2014). "We anticipate that future research on the roles of PRAME and PRAMEY in the crosstalk between the spermatogenesis and immunoresponse will facilitate understanding of both spermatogenesis and tumor developments." (PMID 21347312, 2011). "Our previous analysis demonstrated differences in expression between tumours from survivors and tumours from deceased patients, including four cancer-related genes, ITGB3, CLU, CAPG, and PRAME." (PMID 19775429, 2009). "PRAME, which is expressed in 40% of adult AML patients, has been shown to be a useful marker for MRD particularly where other tumor specific markers are unavailable." (PMID 19662193, 2007). "Experiments addressed on-target/off-tumor recognition of HLA-A2/PRAME double-positive target cells and off-target toxicity against HLA-A2-positive test cells that did not express PRAME, using a cell panel representing vital healthy tissues." (PMID 39858024, 2025). "The complete absence of PRAME staining argues against a highly aggressive tumor biology, which is generally correlated with strong, diffuse PRAME expression." (PMID 41404066, 2025). "This patient had the highest level of PRAME mRNA among all patients at day 28, suggesting that MDG1011 cells may have received particularly strong tumor cell stimulation after IMP infusion." (PMID 41008812, 2025). "In addition, they promote multiple cancer hallmarks and demonstrate high immunogenicity in different tumor types, as exemplified by NY-ESO-1, MAGE-A3 and PRAME." (PMID 39001513, 2024). "The tumour cells were completely negative for MelanA and PRAME while showing only focal SOX10 positivity." (PMID 39001214, 2024). "The recurrent tumour and lymph nodes metastases were completely negative for Melan-A and PRAME, and focally positive for SOX10." (PMID 39001214, 2024). "Immunohistochemical analysis revealed that the tumour cells completely lacked expression of MelanA and PRAME, and focally expressed SOX10." (PMID 39001214, 2024). "The specific targeting of PRAME through T-cell receptor (TCR) therapies, leveraging allogeneic HLA T-cell repertoires, has demonstrated potent anti-tumor reactivity in vitro and in vivo, underscoring the antigen’s viability as a focus for advanced immunotherapeutic strategies." (PMID 39033780, 2024). "PRAME overexpression has recently been explored as a potential therapeutic target for immunotherapy in various neoplasms, although not yet in patients with DICER1 LOF." (PMID 38067388, 2023).
tumor (continued). "PRAME may participate in the EMT process through the regulation of E-cadherin, N-cadherin, and β-catenin, thereby driving tumor metastasis." (PMID 36980687, 2023). "PRAME, which belongs to the CTA gene family, is abnormally expressed in several tumor tissues." (PMID 36980687, 2023). "Tumor cells expressed HMB-45, SOX-10, and PRAME by immunohistochemistry (IHC)." (PMID 37898793, 2023). "The analysis of the mRNA expression levels of 21 CTAs in healthy and tumor ovarian tissue showed an up-regulation in the expression level of AKAP3, MAGEA4, PIWIL1, and PRAME in tumor samples and a down-regulation in the expression level of CTAG1A, CTAG1B, MAGEC1, and PIWIL2." (PMID 37835834, 2023). "Moreover, both in vitro and in vivo studies further confirmed that PRAME can facilitate the proliferation, migration, invasion, and EMT of LSCC cells and promote tumor growth, at least partially by activating PI3K/AKT/mTOR pathways." (PMID 36910848, 2023). "Specific T-cell clones, identified in pre-screening for differential recognition of PRAME-positive vs. -negative cells, were analyzed using a broader tumor cell panel with multiple PRAME-negative or -positive tumor cell lines with varying levels of PRAME mRNA." (PMID 35454906, 2022). "Of tumor germline antigens, we identified PRAME as a potential multi-pediatric cancer target, expressed in many of the tumor types but showing minimal to no expression in all normal organs except testes and ovaries." (PMID 34818552, 2021). "Of note, we did not identify any heterogeneity among CTA-expressing tumours in that all cases which were found to be positive for CT10 and/or PRAME expressed the antigen relatively equally throughout all evaluated TMA cores (both high and low expressing tumours)." (PMID 31485721, 2020). "The identification of a membrane-bound form of PRAME further opens up the possibility to target membrane-bound PRAME-expressing tumor cells with CAR T cell therapy, expanding the spectrum of tools for PRAME-targeted immunotherapy in comparison with the available approaches to target other CTAs." (PMID 31311081, 2019). "Tumor-directed CTLs generated using Torque's modular TAA-priming approach elicit potent cytotoxicity against cancer cells expressing multiple TAA including MART-1 and PRAME." (PMID 30400835, 2018). "IVS confirmed the presence of polyfunctional CD4+ MAGE-specific T cells, as well as reactivity to other tumor antigens PRAME, survivin, HER2 and Wt1 (not seen or tested for in ex-vivo assays)." (PMID 28837000, 2014). "Independent prognostic factors for metastasis-free interval were PRAME expression (P=0.006), age, lymph node status, mastectomy and tumour grade, and vascularisation for the 185 patients who did not receive chemotherapy." (PMID 18648365, 2008). "In addition they reported that RQ-PCR showed a tumor-specific expression of the antigens BAGE, G250 and hTERT, as well as highly tumor-restricted expression for RHAMM, PRAME and WT1." (PMID 19662193, 2007). "Trials evaluating T-cells targeting HLA-restricted PRAME peptides have demonstrated promising anti-tumor activity in PRAME-positive solid tumors, including SS: in the Phase 1b ACTengine IMA203 trial, all three SS patients achieved tumor shrinkage, including one objective response." (PMID 40849585, 2025). "Notably, several tumour types, including spindle cell lipoma and dermatofibrosarcoma protuberans, showed consistently negative PRAME expression." (PMID 38338862, 2024). "Therefore, we interrogated whether direct interaction of PRAME and EZH2 also occurred in DLBCL tumor cells." (PMID 35380993, 2022). "In addition, silencing of PRAME reduced the frequency of CD8+ T cells with expression of the immune checkpoints PD‐1, LAG‐3 and VISTA, indicating that PRAME tumour expression considerably impairs the PD‐L1/PD‐1 axis by dysregulating both the ligand and receptor." (PMID 34612587, 2021).